BCL2 (BCL2 apoptosis regulator)
Diseases named in the same sentence as BCL2 in open-access papers (continued):
Sharing a sentence is not in itself a finding about the gene and the disease.
breast carcinoma (continued). "In contrast, amygdalin administrations alone or in co-administration with tamoxifen could ameliorate breast cancer by declining TNF-α, BcL-2 and attenuating the biochemical parameters." (PMID 40097629, 2025). "In estrogen receptor (ER)-negative MDA-MB-231 breast cancer cells, HK induced apoptosis by inhibiting Bcl-2." (PMID 41296425, 2025). "In another work, BCL2 expression was a predictor of worse outcome in TNBC, while in a subtype-specific breast cancer study, BCL2 status did not significantly influence the 5-year survival in TNBC." (PMID 40806359, 2025). "Upregulation of anti-apoptotic proteins Bcl-2, Bcl-xl, and Mcl-1 in endocrine therapy-resistant, CDK4/6i-resistant, and HER2 TKI-resistant breast cancer cell lines validates this theory." (PMID 40949156, 2025). "Altogether, this study verified the mechanism by which the TRIM25/BRD7/YB1/Bcl-2 axis is involved in the malignant progression and PTX resistance of breast cancer, providing a novel insight into BC development and potential targets for improving the PTX therapeutic resistance." (PMID 41315221, 2025). "In xenograft models of breast cancer, curcumin reduced tumor volume by modulating STAT3 signaling, increasing apoptotic markers (cleaved PARP, caspase-3, -7, -9, Bax, Bid) and decreasing antiapoptotic proteins (Bcl-2, Mcl-1, Bcl-xL)." (PMID 41020838, 2025). "The lead compounds showed a dual mechanism of action by inhibiting S6 kinase and promoting Bcl-2 phosphorylation at 0.9 μM, without significantly affecting hormonal breast cancer targets such as ERα, GREB1, and AR." (PMID 41463068, 2025). "One report demonstrated that oleanolic acid, a triterpenoid obtained from the ethyl acetate fraction of L. stoechas, educed the viability of MCF-7 and MDA-MB-231 breast cancer cells (IC50: 13.09 μg/mL and 160.22 μg/mL, respectively) and triggered apoptosis in MCF-7 cells through Bcl-2 suppression." (PMID 41304951, 2025). "It was found that quercetin suppressed breast cancer stem cells (CD44+/CD24−) derived from the MCF7 cell line through the down-regulation of m-TOR, PI3K, and PI3K-AKT pathways and the decreased expression of Bcl-2 protein and cyclin D1." (PMID 39859345, 2025). "Patients in stages 3 and 4 of breast cancer subtypes such as Her2, Luminal A, and Luminal B who test positive for CCND1, CTSD, EGFR, BCL2, and ESR1 gene expression might benefit in this regard." (PMID 39202273, 2024). "A specific study examining the expression of Bcl-2 and BAX as prognostic markers in breast cancer found that Bcl-2 expression correlated with a better prognosis across all molecular subtypes, including Luminal A breast cancer." (PMID 38256428, 2024). "Additionally, our study explored the roles of other hub genes, including BCL2, PLCB1, ADCY1, and GNAO1, within the HER2-positive breast cancer context." (PMID 39682150, 2024).
breast carcinoma (continued). "Subsequently, we performed qRT–PCR for verification, and the results showed that after adding GluOC into MDA-MB-231 breast cancer cells, the levels of ROCK1, JAK2, PIK3CA, Bcl-2, CREB were significantly increased, while the expression levels of Bax were significantly decreased." (PMID 39054484, 2024). "More importantly, BFC1108 suppressed xenograft growth of human breast cancer cells with high Bcl-2 expression in mice, without any systemic toxicity." (PMID 38329389, 2024). "Additionally, nuclear localisation of BCL2 and BCL-xL has been reported in breast cancer, indicating their potential role in regulating stemness." (PMID 38928195, 2024). "Additionally, in estrogen receptor α (ERα)-dependent breast cancer, KDM6B forms a complex with ERα and binds to ERα sites in the BCL2 enhancer region, leading to BCL2 overexpression following estrogen treatment." (PMID 39620228, 2024). "In addition, by preventing estradiol from upregulating bcl-2, c-myc, and EGFR, SHBG is conducive to the recovery of the apoptosis mechanism of breast cancer cells." (PMID 38465341, 2024). "The effect of NY0123 on breast cancer cells was further detected and showed that CYD0281 significantly inhibits cell viability of MDA-MB-231 cells, and induces cell apoptosis, PARP cleavage, and Bcl-2 BH3 domain exposure in MDA-MB-231 cells." (PMID 37237269, 2023). "Oral PGG treatment of MDA-MB-231 xenograft nude mice suppressed phosphorylated STAT3 in the tumor tissues and downstream target proteins, including VEGF and Bcl-2, which explained the antiproliferative, pro-apoptotic and antiangiogenesis effects of PGG in a breast cancer mouse model." (PMID 37375411, 2023). "Therefore, CYD0281 as a new Bcl-2 BH4 antagonist promoted cell apoptosis through the induced conformational changes of Bcl-2 in HUVECs and breast cancer cells." (PMID 37237269, 2023). "Finally, the MAO-AIs suppressed MAO-A, Bcl-2, and VEGF gene expressions in breast cancer cells relative to untreated cells." (PMID 37841082, 2023). "Moreover, inhibition of miR-122-5p showed a significant effect on the regulation of critical anti-apoptotic proteins such as Bcl-2 and cyclin-dependent kinases (CDK2, CDK4, and CDK6) in breast cancer cells (MCF-7) in response to RSV." (PMID 38026933, 2023). "As expected, a positive correlation between the expression levels of ANXA9 and BCL2 was observed in breast cancer patients (n = 1104), as well as a negative correlation between miR-186-5p and BCL2 (n = 1085)." (PMID 37841425, 2023). "Furthermore, recently, it has been demonstrated that ferulic acid increased bax/bcl-2 ratio and displayed a synergistic activity with epirubicin on apoptosis induction in MDA-MB-231 breast cancer cells." (PMID 36675194, 2023). "The induction of antiapoptotic genes, including B-cell CLL/lymphoma 2 (BCL2), BCL2 related protein A1 (BCL2A1), BCL2 like 1 (BCL2L1), BCL2L2, and myeloid cell leukemia 1 (MCL1), has been observed in multiple cancers, including breast cancer." (PMID 36853387, 2023). "It is also possible that Bcl-2 is an informative marker of ancestry without any role in the pathogenesis of breast cancer, but this seems unlikely given what is known about the function of this protein." (PMID 37370761, 2023).
breast carcinoma (continued). "Surprisingly, our data found that endocrine resistance pathways, which could be divided into 3 functional categories, ERBB2, BCL2, and CCND1, were upregulated in FA-derived breast cancer compared to FA component." (PMID 37328469, 2023). "Similarly, inducing Bcl-2 overexpression in MCF-7 and MDA-MB-468 breast cancer cells by ABT-737, a Bcl-2 antagonist, can increase the efficacy of paclitaxel." (PMID 37569629, 2023). "In addition, amygdalin was shown to increase Bax and decrease Bcl-2 expression in SK-BR-3 and MCF-7 breast cancer cells." (PMID 37762572, 2023). "The five antiapoptotic genes (BCL2, BCL2A1, BCL2L1, BCL2L2, and MCL1) are frequently overexpressed in ER-positive breast cancer cells, and these genes have been used as clinical biomarkers in the diagnosis of breast cancer." (PMID 36853387, 2023). "In breast cancer, a combination of THSG and ADM treatment increased the cell apoptosis by increasing apoptosis related markers including Bax/Bcl-2 and cleaved caspase-3/caspase-3 and decreasing vascular endothelial growth factor/phosphatidylinositol 3-kinase/Akt protein expression." (PMID 37509438, 2023). "To establish whether LHX2 activates the PI3K/AKT/mTOR pathway and apoptosis pathway in breast cancer, we conducted a Western blotting assay to detect the signature proteins in these pathways, including PI3K, p-PI3K, Akt, p-Akt, Bcl-2, and Bax." (PMID 37345110, 2023). "Additional miRNA manipulation using miR-122-5p mimics or inhibitors revealed that miR-122-5p significantly affected the regulation of critical antiapoptotic proteins (B-cell lymphoma 2 [Bcl-2]) and cyclin-dependent kinases (CDK2, CDK4, and CDK6) in resveratrol-resistant breast cancer cells." (PMID 36803831, 2023). "Antiapoptotic proteins (apoptosis gatekeepers, such as BCL-2 and BCL-w): several clinical correlative studies explained the elevated level of antiapoptotic Bcl-2 proteins, and survivin is responsible for the resistance of breast cancer cells." (PMID 37720338, 2023). "Moreover, PGG was found to downregulate the expression of HURP and BCL-2, and increase the expression of BAX to induce apoptosis as an anti-ER breast cancer." (PMID 37050924, 2023). "CAR has also been suggested to promote breast cancer survival in a murine mammary cancer model as adenocarcinomas developed upon syngeneic implantation of preneoplastic mammary tissue show increased CAR and bcl-2 expression compared with non-invasive precursor lesions." (PMID 37306404, 2023). "This suggested that short-term treatment with anti-estrogens through the increase of Bcl-2 sensitizes ER+ breast cancer cells to BH3 mimetics, whereas resistance acquisition leads to a decrease in Bcl-2 levels and shifts the resistance mechanism to other anti-apoptotic factors." (PMID 35053443, 2022). "MTT assay, gene expression analysis (BAX, BCL-2, and β-catenin), apoptosis analysis, TEM, cell cycle assay, ELISA, and cell migration assays were conducted to perform the cell death analysis of lung cancer and breast cancer, compared to the marketed product." (PMID 36457709, 2022). "MiR-21 is a miRNA overexpressed in many types of cancer, particularly breast cancer, and acts as an oncogenic marker by targeting many suppressor genes such as targeting programmed cell death 4 (PDCD4), metalloproteinase inhibitor 3 (TIMP3), PTEN, and Bcl-2." (PMID 35684480, 2022). "SIRT1 has been demonstrated to modulate several intracellular signaling protein molecules, including protein kinase B (PKB), B-cell lymphoma 2 (Bcl-2), metadherin (MTDH), Frizzled 7, EMT-related proteins, and the cluster of differentiation 36 (CD36), in breast cancer cells." (PMID 36291902, 2022).
breast carcinoma (continued). "Notably, the frequency of MCL1 amplification and mRNA expression exceeds both BCL-2 (~9%) and BCL-XL (~27%) across all major subtypes of breast cancer, suggestive of a specific importance of MCL-1 in breast tumourigenesis." (PMID 35349392, 2022). "Dual targeting of BCL2 and CDK4/6 has shown good activity in ER + breast cancer, and so choriocarcinoma patients with intrinsically lower tumour expression for BCL2 may be particularly responsive to treatment with Palbociclib." (PMID 35301407, 2022). "In breast cancer cell lines BT20, MDA-MB-468, and MCF-7, IL-17B induced resistance to paclitaxel, and activation of the extracellular signal-regulated kinase 1/2 (ERK1/2) pathway, leading to the upregulation of B-cell lymphoma 2 (Bcl-2)." (PMID 35954312, 2022). "Prolonged exposure of breast cancer stem cells to rottlerin results in apoptosis, which is correlated with phosphorylated AKT and MTOR suppression, phosphorylated AMPK upregulation and anti-apoptotic BCL2, BCL2L1, XIAP and BIRC2/cIAP1 downregulation." (PMID 36497321, 2022). "In ER+ breast cancer cells, Mcl-1 levels were induced upon treatment with the Bcl-2/Bcl-xL inhibitor ABT-263, whereas MCL1 silencing did not increase Bcl-2 or Bcl-xL, pointing to Mcl-1 as a driver of ABT-263 resistance." (PMID 35053443, 2022). "Azilsartan significantly (p < 0.001) decreased the expression of NF-kB, twist family bHLH transcription factor 1 (TWIST), snail family zinc finger 1 (SNAIL), snail family zinc finger 2 (SLUG) and bcl2 genes, when compared to untreated cells, in MCF-7 and MDA-MB-231 breast cancer cells." (PMID 36431925, 2022). "In this case, we demonstrate that the new flavanone isolated from leaves of Chomolaena tacotana has a promising and selective anti-breast cancer potential that includes the induction of intrinsic apoptosis by downregulation of the anti-apoptotic proteins XIAP and Bcl-2." (PMID 36615253, 2022). "The expression of key markers associated with proliferation (MKI67, PCNA, CCNB1, MYBL2, BUB1, CCND1), apoptosis (BCL2, CASP7, CASP8, CASP9, CASP3, BAX, APAF1), differentiation (CDH1, CD24, EPCAM, ESR1, NGFR, RUNX1), and breast cancer stemness (CD44, ITGA6, DNER, ALDH1A3, ABCG2, PROCR) was assessed." (PMID 35183258, 2022). "Furthermore, MCL1 expression and amplification exceeded that of BCL2 and BCL2L1 (Bcl-xL) in clinical ER+ breast cancer samples." (PMID 35053443, 2022). "In mammary cancer cells, chrysophanol suppresses proliferation and arrests the cell cycle of tumor cells by down-regulating expression of NF-κB p65, p-IκB, and cyclinD1, whereas it promotes PTX-induced apoptosis via the NF-κB/Bcl-2 pathway." (PMID 35911648, 2022). "The proportion of carcinogen-induced mammary tumors arising in bcl-3−/− mice was strongly biased toward a smooth muscle actin negative squamous phenotype characterized by low Bcl-2 expression and absence of NF-κB activity." (PMID 35681213, 2022). "Moreover, everolimus induced apoptosis by decreasing Bcl-2, phosphoinositide 3-kinase (PI3K), protein kinase B (AKT), and mTOR expression levels in breast cancer cells." (PMID 34361836, 2021). "Bcl-2 blocks TRAIL-induced cell death in glioblastoma, neuroblastoma, and breast carcinoma cells." (PMID 34638779, 2021).
breast carcinoma (continued). "The impact of targeting BCL-2 in ER+ breast cancer has been evaluated in clinical phase I and II studies (NCT03900884 & NCT03584009) investigating BCL-2 inhibition by Venetoclax in combination with aromatase/cyclin-dependent kinase inhibitors and hormone therapy, respectively." (PMID 34063475, 2021). "In addition, breast cancer patients with high expression of ATAT1 and MAPK8, RASSF1, BCL2, CXCL8, and FGF1, had a poor prognosis." (PMID 34199510, 2021). "Moreover, BCL-2 was reported to be regulated by ARTN and contributed to trastuzumab resistance of human breast cancer." (PMID 33623790, 2021). "In conclusion, BCL1 expression had no prognostic impact on disease-free survival in breast cancer, whereas BCL2 expression was a significant independent prognostic factor in terms of disease-free survival." (PMID 34099764, 2021). "Furthermore, berberine was utilized against breast cancer as it improved JNK phosphorylation, activated caspase-3, reduced the mitochondrial membrane potential, decreased the expression of Bcl-2, and increased the release of cytochrome c and AIF." (PMID 33920079, 2021). "Bax and Bcl-2 levels for compounds 8e, 8g, and Doxorubicin in MCF-7 breast cancer cell line." (PMID 34833890, 2021). "Nevertheless, the contribution of BCL-2 to MCL-1 inhibition is minor compared to the one observed with BCL-xL, indicating that the anti-apoptotic MCL-1/BCL-xL axis is the predominant one in breast cancer, as previously reported." (PMID 34359829, 2021). "Both miR-15 and miR-16 are considered as tumor suppressors that could be used for therapy of inhibiting BCL2-, CCND1-, and CCND2-overexpressing tumors, e.g., chronic lymphocytic leukemia, breast cancer, prostate, and lung cancer." (PMID 33788050, 2021). "A study analyzed data from 414 breast cancers and reported that BCL2 positivity was not an independent prognosticator in unselected breast cancers." (PMID 34099764, 2021). "al also found that that Bcl-2-negative status was an independent predictor of pathological complete response in breast cancer patients treated with paclitaxel and carboplatin neoadjuvant chemotherapy." (PMID 33392721, 2021). "For example, human breast cancer MCF-7 cells treated with Buthus matensii karsch toxin extract could induce apoptosis by producing caspase 3 and down-regulating Bcl-2." (PMID 34795699, 2021). "Interestingly, an increase of Bcl-2 was observed when PANC-1 cells were treated with GEM, whereas no significant reductions in this protein were observed in MDA-MB-231 and MCF-7 breast cancer cells." (PMID 34959348, 2021). "Remarkably, targeting BCL-2 via siBCL-2 NKExos led to enhanced intrinsic apoptosis in breast cancer cells, without affecting non-malignant cells." (PMID 34063475, 2021). "It was demonstrated that SPS could promote apoptosis in MCF-7 breast cancer cells by regulating the expression of Bcl-2 and Bax, and also induce apoptosis by blocking the PI3K/Akt/mTOR pathway in MDA-MB-435 human breast cancer cells." (PMID 34744747, 2021). "The synergistic effect of the combination therapy of TQ and TRAIL significantly inhibit the genetic expressions of Bcl2 gene and upregulate the genetic expressions of Cas-8 and FADD genes up on breast cancer MCF-7 and MDA-MB-231 cell lines treated for 24 h with noted TQ or/and TRAIL concentrations." (PMID 34582654, 2021). "Dual BCL-2/BCL-xL inhibitors (ABT-737 or ABT-263/Navitoclax) or selective inhibitor of BCL-xL (WEHI-539) are also available and some have already been shown to potentiate the effects of chemotherapy in breast cancers in preclinical studies." (PMID 31937780, 2020).